FAM131B-AS2 (FAM131B antisense RNA 2)
Synonyms: PCAL7
Gene: Long non-coding RNA gene on chromosome 7 (143,365,046 to 143,382,339, reverse strand). Ensembl gene ENSG00000232533.
Diseases named in the same sentence as FAM131B-AS2 in open-access papers:
FAM131B-AS2 is named in the same sentence as 2 diseases in open-access papers, as found by Europe PMC text mining. Sharing a sentence is not in itself a finding about the gene and the disease.
FAM131B-AS2 shares sentences with these, for which no sentence is quoted: prostate carcinoma (1 paper); tumor (1).